PTGS2 (prostaglandin-endoperoxide synthase 2)
Diseases named in the same sentence as PTGS2 in open-access papers (continued):
Sharing a sentence is not in itself a finding about the gene and the disease.
colon carcinoma (continued). "In kidney and colon cancer models, NFAT5 has been shown to upregulate cyclooxygenase 2 (COX2; PTGS2), an enzyme of paramount functional importance in both normal and malignant endometrial tissue." (PMID 38612478, 2024). "We filtered four genes (BDNF, PTGS2, CTNNB1, and GSK3B) from the colon tumor and matched normal RNA-seq data, estimated the differences in fold change, and performed a t-test to determine the p value representing significant differences." (PMID 35054980, 2022). "The results indicated that some genes play an important role in the colon cancer patients' survival and prognosis, including VEGFA, PTGS2, and CAPS3." (PMID 34194533, 2021). "Fusobacterium-related genes, including PTGS2 (COX-2), IL1b, IL6, IL8 and TNF, are expressed not only in colon cancer but also in cultures of human and mouse cell lines in vitro known as the central link between inflammation and cancer." (PMID 33823861, 2021). "Our results describe for the first time the molecular pathway correlating PTGS2 and PTGES in colon cancer progression." (PMID 26498686, 2015). "For instance, EGFR activation results in PTGS2 (COX-2) expression at both mRNA and protein levels in a rat intestinal epithelial cell and colon cancer cells in vitro." (PMID 24213116, 2011). "The focus on the regulatory regions of the gene is justified by the fact that PTGS2 mRNA is very unstable, and an increase in its stability promotes COX-2 expression in colon cancer cells." (PMID 21059239, 2010). "Interestingly, independent study observed that HuR binds to PTGS2 mRNA and HuR silencing decreases the expression of PTGS2/COX-2 in human colon carcinoma cells." (PMID 35011584, 2021). "scRNA-seq identified prostaglandin-endoperoxide synthase 2 (Ptgs2)-expressing fibroblasts that expand tumor-initiating stem cells via YAP signaling, whereas ablation of Ptgs2 diminished the occurrence of the small intestine and colon cancers." (PMID 34760886, 2021). "We have not proven that apigenin and naringenin could exert anti-colon cancer effects via regulating PTGS2 and MMP9 with additional experiments in this study." (PMID 35847793, 2022). "Additional findings supporting this mechanism included reduced colon tumor formation in muscarinic agonist-treated mice lacking intestinal epithelial cell βPix expression and reduced MYC, CCND1 and PTGS2 gene and protein expression in colon adenocarcinomas resected from those mice." (PMID 39493347, 2024).
gastric cancer (91 papers, 2001 to 2025). A primary or metastatic malignant neoplasm involving the stomach. "Studies have shown that Ptgs2 expression in gastric cancer patients is associated with poor prognosis." (PMID 40568084, 2025). "In gastric cancer, PTGS2 is upregulated and associated with tumor progression and poor prognosis." (PMID 38675376, 2024). "The PTGS2 expression was associated with increased lipid peroxidation in gastric cancer cells." (PMID 35359830, 2022). "In the realm of clinical translation, we leveraged the genetic signatures of JUN, HIF1A, and PTGS2 to establish a predictive model tailored for gastric cancer prognosis." (PMID 40391580, 2025). "Following the initial confirmation that the active components of Hairyvein Agrimonia had a sound docking basis with the gastric cancer target protein PTGS2, we further carried out in vitro validation experiments using gastric cancer cells." (PMID 40391580, 2025). "Upon establishing the robust docking interactions between the active components of Hairyvein Agrimonia and the target protein PTGS2 in gastric cancer, we proceeded with rigorous in vitro validation experiments employing gastric cancer cells." (PMID 40391580, 2025). "Noteworthy findings from diverse studies have underscored the aberrant upregulation of PTGS2 in human gastric cancer tissues, highlighting its strategic involvement in disease pathogenesis." (PMID 40391580, 2025). "Based on the RNA sequencing data, PTGS2 (cyclooxygenase-2 or COX-2) was identified as an upregulated gene in gastric cancer." (PMID 40141751, 2025). "Intriguingly, the integrative predictive model hinging upon the genetic signatures of JUN, HIF1A, and PTGS2 emerges as a robust prognostic indicator correlating with poorer clinical outcomes in gastric cancer patients." (PMID 40391580, 2025). "The RNA sequencing data highlight several key proteins—HIF1A, HSP90AA1, PTGS2, MMP9, and ERBB2—which are associated with various stages of gastric cancer progression and align with established biomarkers and pathways." (PMID 40141751, 2025). "The target proteins implicated in gastric cancer, specifically HIF1A, HSP90AA1, MMP9, ERBB2, and PTGS2, were matched with the key metabolites from the Vaccinium genus, including cyanidin 3-O-glucoside, ursolic acid, resveratrol, scopoletin, and (+)-catechin." (PMID 40141751, 2025). "Studies have shown that PTGS2 expression increases in gastric cancer cells treated with tanshinone IIA (Tan IIA), a compound derived from traditional Chinese medicine." (PMID 38675376, 2024). "Further research is needed to fully understand the mechanisms and functional implications of PTGS2 in gastric cancer and its potential as a therapeutic target." (PMID 38675376, 2024). "Fer-1, a lipid peroxidation inhibitor, significantly attenuated Tan IIA caused increased lipid peroxidation and Ptgs2, Chac1 expression, which indicated that Tan IIA indeed induced ferroptosis in BGC-823 and NCI-H87 gastric cancer cells." (PMID 32776119, 2020). "The positive correlations between DNMT3A/DNMT3B with PTGS2 was validated in an independent gastric cancer cohort (GSE27342)." (PMID 31534549, 2019). "Hsa-miR-143-5p exhibits a strong tumor suppressive effect and has been shown to act as anti-oncomirs in gastric cancer and directly target prostaglandin-endoperoxide synthase 2 (COX-2)." (PMID 28927412, 2017). "Furthermore, the prognostic models constructed by the carcinogenic genes JUN, HIF1A, and PTGS2 are significantly correlated with the survival time of gastric cancer patients." (PMID 40391580, 2025). "Collectively, these findings underscore the potential therapeutic efficacy of Hairyvein Agrimonia in antagonizing gastric cancer progression, potentially mediated through its modulation of PTGS2 activity and its interplay with key molecular pathways implicated in disease pathogenesis." (PMID 40391580, 2025).
gastric cancer (continued). "Collectively, these compelling findings underscore the pivotal role of the JUN, HIF1A, and PTGS2 genes as promising clinical prognostic markers for patients grappling with gastric cancer, heralding a paradigm shift in personalized prognostication strategies within the oncological landscape." (PMID 40391580, 2025). "We first found that Tan IIA could induce ferroptosis in BGC-823 and NCI-H87 gastric cancer cells which was characterized by increased lipid peroxidation and Ptgs2, Chac1 expression." (PMID 32776119, 2020). "Moreover, compelling evidence from experimental models has underscored the therapeutic potential of selective PTGS2 inhibitors such as celecoxib in impeding gastric tumor development, offering promising avenues for targeted intervention strategies in the realm of gastric cancer therapeutics." (PMID 40391580, 2025). "PTGS2 is upregulated in gastric cancer and may play a role in tumor progression." (PMID 38675376, 2024). "Therefore, it can be inferred from these results that AR may improve GU and even prevent it from developing into gastric cancer by regulating COX2/PTGS2 and PGE2." (PMID 37109624, 2023). "PTGS2 (COX2) is notably involved in intestinal metaplasia, extensive atrophy, and early gastric cancer, aligning with its established role in promoting tumor progression and inflammation in advanced colorectal cancer." (PMID 40141751, 2025). "Asporin has been shown to strongly inhibit apoptosis, promote growth in gastric cancer cells, and selectively promote LEF1 binding to activate the promoters of PTGS2, IL-6, and WISP1 to facilitate their transcription." (PMID 39296492, 2024). "The differences in the expression of hub genes, PTGS2, MMP9, MMP2, and CXCR4 genes were higher than normal gastric tissues in gastric cancer, and PPARG gene was lower than normal gastric tissues." (PMID 38457601, 2024). "To further examine the anti-apoptosis mechanism of the volatile oil of R. rubescens in gastric cancer cells, we performed western blotting to detect the four core targets, TNF, IL1B, MPP9 and PTGS2." (PMID 36200190, 2022). "Here, we found that PAFAH1B3 knockdown in gastric cancer cells downregulated the levels of IRS1, Myc, HMGB1, and PTGS2, which were reported to serve as oncogenes in many types of cancers." (PMID 33732641, 2021). "The compounds with high recommendation value in the network mainly have the highest acacetin, wogonin, baicalein, Salvigenin, and Moslosooflavone value ranking of gastric cancer disease-related targets mainly NOS2, PTGS1, PTGS2, DPP4, and so on." (PMID 34421596, 2021). "We found that the volatile components of R. rubescens could inhibit the activity of gastric cancer cells, possibly by regulating the levels of TNF, IL1B, MPP9 and PTGS2." (PMID 36200190, 2022). "Our findings indicate that the volatile oil of R. rubescens may promote the apoptosis of gastric cancer cells by inhibiting the expression of TNF, IL1B, MPP9, and PTGS2." (PMID 36200190, 2022).
lung carcinoma (75 papers, 2003 to 2025). "Polymorphisms rs2031920 and rs6413432 associate with prostaglandin G/H synthase 2 gene (PTGS2) polymorphisms for lung cancer risk in specific human groups." (PMID 34298760, 2021). "Polymorphisms in the PTGS2 gene have been associated with various diseases, including inflammatory bowel disease and cancer of the lung, colorectum, and breast." (PMID 17214885, 2007). "Decreased expression of PPARG and increased expression of PTGS2 (Prostaglandin Endoperoxide Synthase 2) has also been shown to be associated with the prognosis of lung cancer, treatment with PPARG agonists lead to a decrease in the levels of PTGS2 thus inhibiting the growth of NSCLC." (PMID 31263479, 2019). "Therefore, we further explored the effects and the underlying mechanisms of PTGS2 inhibitor (celecoxib) on the antitumor activity of cisplatin using the lung cancer xenograft models." (PMID 31440159, 2019). "Molecular docking analysis was conducted to evaluate the binding affinities of the top 10 MQLEO-derived compounds against four lung cancer-associated targets (ESR1, CASP3, PPARG, and PTGS2)." (PMID 40573169, 2025). "Preclinical studies have confirmed that 3’-methylated HQi-sRNA-2 significantly inhibits the proliferation, migration, and invasion of NCI-H460 human lung cancer cells by targeting COX-2/PTGS2 and downregulating the PI3K/AKT signaling pathways." (PMID 40362513, 2025). "Next, PTGES, ST8SIA1 and PTGS2 expression levels were evaluated in patients with lung cancer (GSE31210) and IPF using microarray datasets." (PMID 39417702, 2024). "In contrast, excessive production of prostaglandin-endoperoxide synthase-2 (PTGS2) leads to lung cancer progression, which subsequently leads to metastasis and angiogenesis." (PMID 38731403, 2024). "Overproduction of PTGS2 and the prostaglandins was observed in lung cancer and involved in lung carcinogenesis and progression via promoting angiogenesis, metastasis, and immunosuppression." (PMID 31440159, 2019). "The aim of this study was to investigate the association of five extensively-studied polymorphisms in PTGS2 (rs689466, rs5275, rs20417) and CYP2E1 (rs2031920, rs6413432) genes with lung cancer risk in a large northeastern Chinese population." (PMID 22761909, 2012). "Recently, several global meta-analyses have summarized the individual findings on PTGS2 and CYP2E1 genes and confirmed the significantly protective effect of rs5275, rs2031920 and rs6413432 mutant alleles on lung cancer." (PMID 22761909, 2012). "To expand the findings, we reported a potential synergism between PTGS2 and CYP2E1 genes on lung cancer risk, as reflected by haplotype and interaction analyses." (PMID 22761909, 2012). "Many studies have evaluated the association of polymorphisms in PTGS2 and CYP2E1 genes with lung cancer; however, the results have been inconsistent, and the biological effects based on statistical reasoning are still elusive." (PMID 22761909, 2012). "Our findings demonstrated a potentially synergistic association of PTGS2 and CYP2E1 polymorphisms with the underlying cause of lung cancer in northeastern Chinese." (PMID 22761909, 2012). "Due to these important functions, PTGS2 and CYP2E1 genes were investigated as logical candidates for lung cancer susceptibility." (PMID 22761909, 2012). "In this study we found significant associations of PTGS2 and CYP2E1 polymorphisms with the susceptibility to lung cancer in northeastern Chinese." (PMID 22761909, 2012). "A total of 83 potential targets of ROB in lung cancer were collected and further screened by using Cytoscape software, and 7 targets of PTGS2, CYP19A1, PTGS1, AR, CYP17A1, PTGES and SRD5A1 were obtained as hub genes and 7 hub targets had good binding energy with ROB." (PMID 39450260, 2024).
lung carcinoma (continued). "The single nucleotide polymorphisms of COX-2 gene, also known as PTGS2, which encodes a pro-inflammatory factor cyclooxygenase-2, alter the risk of developing multiple tumors, but these findings are not consistent for lung cancer." (PMID 35450217, 2022). "Lung cancer patients with a high expression level of PTGS2, a classic PGF2α-related gene, in tumours exhibited a high overall survival rate, implying that PGF2α might be positively correlated with good prognosis in lung cancer patients." (PMID 35052569, 2021). "Overproduction of PTGS2 has also been observed in lung cancer for immunosuppression." (PMID 34098948, 2021). "In addition, TLR4 signaling promotes proliferation of A549 lung cancer cells through PTGS2/COX-2 (prostaglandin-endoperoxide synthase 2 (prostaglandin G/H synthase and cyclooxygenase)) and epidermal growth factor receptor (EGFR) activation." (PMID 32384667, 2020). "Specifically, this effect of Cmpd17b may be independent of diabetes as it has been reported that upregulation of the endogenous FPR agonist, Annexin A1, reduces Ptgs2 expression in lung cancer cells." (PMID 32085666, 2020). "In this study prostaglandin-endoperoxide synthase 2 (PTGS2) and cytochrome P450, family 2, subfamily E, polypeptide 1 (CYP2E1) were selected as candidate genes susceptible to lung cancer based on their critical involvement in the mechanism of lung carcinogenesis." (PMID 22761909, 2012). "Moreover, genotyping data from the PTGS2 and CYP2E1 genes, incorporating the haplotype and synergism analytical strategy would facilitate the identification of individuals at high risk of developing lung cancer in future clinical screening." (PMID 22761909, 2012). "The upregulated genes included CYP4F3, IL1RL1, PTGS2, and CXCL8, which are related to inflammation; HKDC1, MYEF2 and CYP1A1, which are related to hepatocarcinoma or lung carcinoma; and SLC7A11 and NEFM, which are related to neuronal damage." (PMID 33247188, 2020). "This study provides supporting evidence for further investigation on pathophysiological mechanisms of PTGS2 and CYP2E1 genes in lung cancer." (PMID 22761909, 2012). "The hub targets of ROB action in lung cancer were further analyzed by combining 14 targets from Degree≥6, 10 targets each from MCC and MNC algorithms, and finally 7 common targets such as PTGS2, CYP19A1, PTGS1, AR, CYP17A1, PTGES and SRD5A1 were obtained from the final screening." (PMID 39450260, 2024). "Since PNO1 knockdown inhibited the expression of PTGS2, a gene involved in inflammation, we sought to examine the effects of inhibiting PNO1 on the expression of inflammatory cytokines (IL‐1α and IL‐8) in lung cancer cells." (PMID 36625087, 2023). "Previous studies have shown that the inhibition of PTGS2 might play a beneficial role in the treatment of NSCLC, such as improving the overall response rate of advanced NSCLC and suppressing the metastasis of lung cancer cells." (PMID 32503508, 2020). "To verified which gene(s) can be targeted by miR-26a-5p, we overexpressed miR-26a-5p in H1299 cells and found that only PTEN expression was decreased and CDK8 and PTGS2 expression did not change in H1299 cells, implying that only PTEN may be a target of miR-26a-5p in lung cancer." (PMID 33407724, 2021).